Y_RNA (Y RNA )
Gene: Miscellaneous RNA gene on chromosome 10 (52,852,607 to 52,852,703, forward strand). Ensembl gene ENSG00000201196.
Homologues: Orthologues: chimpanzee Y_RNA (98% identical), macaque Y_RNA (92% identical). Paralogues in human: RNY4 (87% identical), RNY4P19 (87% identical), RNY4P37 (87% identical), Y_RNA (87% identical), RNY4P6 (86% identical), RNY4P7 (86% identical), Y_RNA (86% identical), RNY4P10 (85% identical), RNY4P25 (85% identical), Y_RNA (85% identical), RNY4P27 (84% identical), RNY4P9 (84% identical), and 89 more.